AXL (AXL receptor tyrosine kinase)
Diseases named in the same sentence as AXL in open-access papers (continued):
Sharing a sentence is not in itself a finding about the gene and the disease.
endometriosis (continued). "Similar to what we observed for AXL, the PI3K-Akt signaling pathway was either inactive or weakly active in eutopic endometrium, whereas it was consistently activated in endometriosis." (PMID 19055724, 2008). "Our data show that AXL and SHC1 are differentially expressed in endometriosis implicating the PI3K and MAPK pathways in this disease." (PMID 19055724, 2008). "AXL, a member of Tyro3/AXL/Mer (TAM) receptor tyrosine kinase (RTK) family, was shown to be upregulated in endometriosis by SAGE and IHC in the present study." (PMID 19055724, 2008). "As overexpression of AXL and SHC1 theoretically activates both PI3K-Akt and MAPK pathways, dysregulation of these genes in human endometriosis may correspond to oncogenic activation of K-ras or biallelic losses of Pten in the mouse model of the disease." (PMID 19055724, 2008). "Next, we investigated the possibility that downstream pathways in which AXL and SHC1 are involved, PI3K/Akt and MAPK respectively, may be activated in endometriosis." (PMID 19055724, 2008). "In human endometriosis, the PI3K-Akt and MAPK signaling pathways may be activated via overexpression of AXL and SHC1, respectively." (PMID 19055724, 2008). "Moreover, these pathways have been shown to enhance the transcriptional activity of ERβ Therefore, we propose that kinases activated by the PCB126/AXL/GAS6 axis may, in turn, activate ERβ to promote endometriosis progression." (PMID 40951281, 2025). "Furthermore, the proto-oncogenes AXL, SHC1, and JUND are elevated in endometriosis." (PMID 19055724, 2008).
Flavivirus Infections (4 papers, 2013 to 2023). Infections with viruses of the genus FLAVIVIRUS, family FLAVIVIRIDAE. "TAM family and TIM family genes, mainly including AXL, TYRO3, MERTK and TIM-1, were suggested as putative host factors in flavivirus infection of human host cells." (PMID 37684223, 2023). "Additionally, some investigations have also suggested that the T-cell immunoglobulin and mucin domain (TIM) and TYRO3, AXL and MER (TAM) can enhance flavivirus infection by binding to PtdSer on the virion surface rather than E glycoprotein." (PMID 31718685, 2019).
Hypertension (4 papers, 2019 to 2025). The presence of chronic increased pressure in the systemic arterial system. "Preclinical models demonstrate that AXL inhibitors, including small molecules and monoclonal antibodies, effectively reduce hypertension, proteinuria, and placental inflammation." (PMID 39996749, 2025). "These levels were significantly correlated with markers of inflammation, hypertension, and proteinuria, emphasizing the role of Gas6/AXL signaling in the systemic manifestations of the disease." (PMID 39996749, 2025). "Pregnant rats were administered Gas6 to induce PE-like symptoms such as hypertension and proteinuria; a subset also received the AXL inhibitor R428." (PMID 40862707, 2025). "AXL mediates the vascular response to mechanical and chemical insults and hypertension and contributes to vascular calcification." (PMID 31181097, 2019).
influenza infection (4 papers, 2016 to 2025). "Gab1 knockdown in vivo, or LY294002 (a PI3K inhibitor), abolishes the PROS1/AXL-induced protective activity against lethal influenza infection in mice." (PMID 41158072, 2025). "Similar to our findings, a recent study described AXL-expressing murine airway macrophages at homeostatic conditions, which increased after influenza infection, thereby preventing excessive tissue inflammation through efferocytosis." (PMID 31822557, 2020). "Flow cytometry analyses revealed that AXL is expressed in both of these DC subsets during influenza infection." (PMID 27350258, 2016). "Type I IFN may also diminish DC maturation, reduce production of IL-1β, and weaken antiviral T cell immunity in AXL receptor tyrosine kinase deficient (Axl−/−) mice during WNV and influenza infection." (PMID 31623175, 2019). "The findings also suggest that using drugs that block AXL to treat infections with certain viruses, including influenza and West Nile Virus, might do more harm than good." (PMID 27350258, 2016). "However, the role of PROS1/AXL signaling in influenza A virus (IAV) infection and infection-induced lung injury is largely unknown." (PMID 41158072, 2025).
liposarcoma (4 papers, 2015 to 2024). A usually painless malignant tumor that arises from adipose tissue. "Taken together, these findings support an autocrine mechanism of AXL activation via GAS6 secretion in liposarcoma disease progression." (PMID 26573603, 2015). "In addition, a liposarcoma tumor sample among the 1,127 tumors with identified driver origins after the initial analyses exhibited a fold change in AXL expression approaching the cutoff level (FC = 4.97) and had four genomic copies of this gene." (PMID 28377632, 2017). "Stable AXL knockdown not only decreased migratory and invasive characteristics of DDLPS and PLS cells in vitro but also significantly diminished tumorigenicity of two dedifferentiated liposarcoma xenograft models in vivo." (PMID 26573603, 2015).
lymph node metastasis (4 papers, 2016 to 2023). "AXL expression was also positively correlated with lymph-node metastasis, since patients with N1 cholangiocarcinoma (metastasis found in 1–3 axillary lymph nodes) had higher AXL expression than N0 patients (p = 0.0195)." (PMID 36980768, 2023). "Expression of MERTK and/or AXL provides a survival advantage for NSCLC cells and correlates with lymph node metastasis, drug resistance, and disease progression in patients with NSCLC." (PMID 34830794, 2021). "However, the combination of an AXL-targeting treatment with the existing standards of care, such as radio-chemotherapy, should be further explored in patients that are AXL-positive or present with lymph node metastases to prevent further disease progression and to offer novel therapeutic options." (PMID 28025482, 2016).
metastatic prostate carcinoma (4 papers, 2016 to 2023). A carcinoma that arises from the prostate gland and has spread to other anatomic sites. "AXL was shown to be highly expressed in metastatic prostate cancer and its interaction with Gas6 was suggested to play a role in establishing tumor dormancy in the bone marrow microenvironment." (PMID 26762579, 2016). "Moreover, a correlation between HIF-1 and AXL expression has been shown in metastatic prostate cancer, where hypoxia stabilized the AXL protein." (PMID 28251492, 2017). "The frequent co–overexpression of AXL and MIG6 in metastatic prostate cancer, supported by Oncomine data, further reinforces our hypothesis." (PMID 37834326, 2023). "Of note, hypoxia may not only act on transcriptional regulation of AXL but also stabilize GAS6/AXL signaling by preventing GAS6-mediated downregulation of AXL, at least in DU145 and PC3 metastatic prostate cancer cell lines." (PMID 35572601, 2022).
pancreatic ductal adenocarcinoma (4 papers, 2015 to 2023). An infiltrating adenocarcinoma that arises from the epithelial cells of the pancreas. "Frequent overexpression of both molecules, Gas6 and AXL, has been detected in Pancreatic Ductal Adenocarcinoma (PDA) cells and was linked to a poor prognosis in patients with stage II PDA." (PMID 37469409, 2023). "In human pancreatic cancer, MAP4K1 loss is associated with the development of invasive pancreatic ductal adenocarcinomas, and its restoration in pancreatic ductal adenocarcinoma cells inhibits cell proliferation and reduces invasion potential by inducing degradation of oncogenic kinase AXL." (PMID 37734869, 2023). "High AXL expression in 76% (32/42) of pancreatic ductal adenocarcinoma was reported, especially present in invasive cells." (PMID 36261437, 2022).
rheumatoid arthritis (4 papers, 2017 to 2024). A chronic, systemic autoimmune disorder characterized by inflammation in the synovial membranes and articular surfaces. "miR-34a regulates vascular smooth muscle cell calcification by inhibiting AXL, and upregulation of miR-34a was shown to significantly decrease the levels of AXL in patients with rheumatoid arthritis (RA) compared with those of healthy individuals." (PMID 34734092, 2021).
Autoimmunity (3 papers, 2016 to 2025). The occurrence of an immune reaction against the organism's own cells or tissues. "Loss of AXL expression on antigen-presenting cells has been linked to autoimmunity." (PMID 31822557, 2020). "AXL dendritic cells, the smallest group of dendritic cells identified in our study, are a recently identified subset of dendritic cells with unique properties, and their role in autoimmunity is an emerging area of research." (PMID 40703454, 2025).
brain cancer (3 papers, 2018 to 2025). A primary or metastatic malignant neoplasm affecting the brain. "The receptor molecule AXL, a member of the TAM (Tyro3, AXL, Mer) family of receptor tyrosine kinases, plays a role in cancer progression, metastasis and treatment resistance, and high AXL expression is often linked to a poorer prognosis in brain cancer patients." (PMID 38251196, 2023). "Since 2009, the FDA has approved a number of multi-kinase inhibitors that target angiogenic growth factor receptors (e.g., VEGFR, PDGFR, FGFR, RET, c-KIT, MET, AXL and others) for treatment of malignant diseases, including brain cancer." (PMID 40076810, 2025). "Therapeutic goals including cancer stem cells (CSC), phenotypic shifts, EZH2/AXL/TGF-β axis activation, miRNAs and exosomes are relevant to GBM metastasis to develop novel targeted therapeutics for GBM and other brain cancers." (PMID 29642503, 2018).
cholangiocarcinoma (3 papers, 2023 to 2025). A carcinoma that arises from the intrahepatic biliary tree (intrahepatic cholangiocarcinoma) or from the junction, or adjacent to the junction, of the right and left hepatic ducts (hilar cholangiocarcinoma). "Data analysis from UALCAN showed that compared to normal tissues, tumor tissues from cholangiocarcinoma patients had significantly higher AXL expression (p = 0.0382)." (PMID 36980768, 2023). "A recent phase II trial in bile duct cancer with cabozantinib, a multi-kinase inhibitor targeting VEGFR2, MET and AXL, supports targeting receptor tyrosine kinases such as AXL as possible therapeutic targets to treat cholangiocarcinoma." (PMID 36980768, 2023). "Our study demonstrated that AXL expression is highly upregulated in cholangiocarcinoma patients and potentially can be used as a prognostic marker." (PMID 36980768, 2023). "To determine the role of AXL in bile duct cancer patients, we first evaluated mRNA expression of AXL in patient tissues with normal liver and cholangiocarcinoma using UALCAN, a web-based platform for differential gene expression based on publicly available omics data (TCGA, MET500, CPTAC and CBTTC)." (PMID 36980768, 2023).
cognitive decline (3 papers, 2022 to 2026). "Similarly, higher levels of AXL, MERTK, GAS6, LPL, CST7 and CSF1 predicted slower tau accumulation and/or cognitive decline in the A+T+ group." (PMID 37118533, 2022).
End Stage Liver Disease (3 papers, 2020 to 2025). Final stage of a liver disease when the liver failure is irreversible and LIVER TRANSPLANTATION is needed. "The expression of p-AXL was down-regulated by immunohistochemical staining in livers obtained from patients with the end-stage liver disease caused by massive and chronic alcohol consumption." (PMID 39897049, 2025). "AXL expression on liver macrophages correlated negatively with disease severity scores (Child-Pugh and Model of End-Stage Liver Disease [MELD] scores) and a marker of inflammation (C-reactive protein)." (PMID 37004869, 2023).
endothelial dysfunction (3 papers, 2018 to 2025). In vascular diseases, endothelial dysfunction is a systemic pathological state of the endothelium (the inner lining of blood vessels) and can be broadly defined as an imbalance between vasodilating and vasoconstricting substances produced by (or acting on) the endothelium. "The soluble form of AXL (sAXL), a tyrosine kinase receptor, is considered a biomarker of endothelial dysfunction and associated with myocardial ischemia and heart failure." (PMID 30245754, 2018). "Elevated levels of Gas6 and soluble AXL in maternal plasma have been observed in women with severe PE, which correlate with markers of endothelial dysfunction and systemic inflammation." (PMID 40862707, 2025). "Notably, co-treatment with the AXL inhibitor R428 appeared to reverse these clinical manifestations, aligning with its ability to mitigate platelet aggregation and endothelial dysfunction in this pathway." (PMID 40862707, 2025). "Evaluate the clinical yield of high-sensitivity cardiac troponin T (hs-cTnT), marker of cardiomyocyte damage, and the soluble form of AXL (sAXL), biomarker of endothelial dysfunction, to assess the prognosis of long-term cardiovascular (CV) events occurring after HTx." (PMID 30245754, 2018).
fibrosis (3 papers, 2020 to 2024). the formation of excess fibrous connective tissue in an organ or tissue in a reparative or reactive process. "Our previous results identified the GAS6/TAM pathway as a relevant mechanism activated in patients suffering from MASH, which could be prevented by targeting AXL as demonstrated in experimental animal models of fibrosis and MASH." (PMID 38817615, 2024). "Since our present results reveal the presence of serum sAXL as an early marker of MASLD, even before fibrosis detection, we wanted to evaluate if AXL inhibition could be effective in protecting the liver as soon as serum sAXL started increasing." (PMID 38817615, 2024).
Insulin resistance (3 papers, 2014 to 2025). Increased resistance towards insulin, that is, diminished effectiveness of insulin in reducing blood glucose levels. "The present study was designed to explore the effects of GAS6 and AXL gene polymorphisms on adiposity, systemic inflammation, and insulin resistance in adolescents." (PMID 24696684, 2014). "In conclusion, we indicate an association between the GAS6 and AXL polymorphisms with adiposity, circulating inflammatory markers, and insulin resistance of adolescents, especially in boys." (PMID 24696684, 2014). "In this study, a strong association between GAS6 and AXL polymorphisms with body adiposity, systemic inflammation, and insulin resistance was identified among boys." (PMID 24696684, 2014). "In conclusion, GAS6 and AXL polymorphisms are associated with adiposity, systemic inflammation, and insulin resistance in adolescents, especially in boys." (PMID 24696684, 2014). "In order to address this issue, we conducted a community-based study to determine whether common variations in the GAS6 and AXL genes correlate with adiposity, systemic inflammation, insulin resistance among adolescents." (PMID 24696684, 2014). "AXL also interacted with several other miRNAs related to DN: miR-499a and heterogeneous nuclear ribonucleoprotein A2B1 (hnRNPA2B1), as well as its predicted interaction with miR-363 that was related to insulin resistance." (PMID 41233312, 2025). "This suggests that AXL may drive increased expression of SOCS3, which has been implicated in genotype 1 mediated insulin resistance and treatment non-response." (PMID 26313459, 2015).
lupus (3 papers, 2013 to 2022). "ADAM10, one of the genes enriched in cellular protein localization, has been reported to mediate the cleavage of AXL receptor tyrosine kinase in PBMC of SLE patients, exacerbating the progression of lupus." (PMID 34150746, 2021). "The minor cluster #11 expressed AXL, IRF4, IRF7, and CD5 genes previously found in AS-DC, Pre-DC, or pDC45,46, but was absent from blood samples; #11 better aligned to transitional DC47 and were mostly observed in HNSCC and in Lupus." (PMID 35418195, 2022).
myeloid malignancies (3 papers, 2023 to 2024). "The receptor tyrosine kinase AXL is linked to the pathogenesis of myeloid malignancies and mediates chemotherapy resistance." (PMID 37735558, 2023). "Therefore, a small molecule inhibitor of AXL, bemcentinib, which selectively binds to the intracellular catalytic kinase domain of AXL, is a licensed therapy currently in multiple Phase II trials for the treatment of breast, lung, and myeloid neoplasms." (PMID 38261406, 2024).
neurofibroma (3 papers, 2014 to 2020). An intraneural or extraneural neoplasm arising from nerve tissues and neural sheaths. "We previously found that the receptor AXL is expressed in 91% of MPNSTs and nearly 95% of neurofibromas (the precursor lesions for MPNSTs), which suggests that AXL dysregulation is an early event in MPNST development." (PMID 33283192, 2020). "Previously, we have shown that high level of the soluble fraction from the extracellular domain of AXL (sAXL) was found in patients with plexiform neurofibroma and with MPNST." (PMID 32252313, 2020). "The other two MPNST samples (from two other patients) in this study had high levels of AXL, as did 1 out 4 dermal neurofibromas." (PMID 25551830, 2014). "In support of the dual targeting of AXL and MEK1/2, NF1–associated MPNSTs with ERK activation grow more rapidly than do those without ERK activation, suggesting that MEK signaling is an early event in the transformation of neurofibroma into MPNST." (PMID 33283192, 2020). "In the present study, we examined AXL activation in an established MPNST and neurofibroma tissue microarray (TMA), patient-derived MPNST cell lines, and human MPNST patient-derived derived xenograft (PDX) models." (PMID 33283192, 2020). "Our previous study found that AXL is overexpressed in both human MPNST and neurofibroma samples." (PMID 33283192, 2020).
neurofibromatosis type 1 (3 papers, 2010 to 2020). A clinically heterogeneous, neurocutaneous genetic disorder characterized by cafe-au-lait spots, iris Lisch nodules, axillary and inguinal freckling, and multiple neurofibromas. "Demographic data, tumor burden and level of soluble AXL in patients with neurofibromatosis type 1." (PMID 25551830, 2014).
oesophageal cancer (3 papers, 2014 to 2020). "Overexpression of AXL in esophageal carcinoma has been shown to promote cisplatin resistance through regulation of c-ABL/p73 signaling." (PMID 25337673, 2014).
oral cancer (3 papers, 2021 to 2024). "This regulation, which enhances nuclear β-catenin translocation and upregulates SNAIL, drives oral cancer aggressiveness and stemness, suggesting the miR-34a-5p/AXL axis as a potential therapeutic target." (PMID 39200273, 2024). "In oral cancer cells, the miR-34a-5p/AXL axis increased aggressiveness and could be a therapeutic target for OSCC by affecting AKT, GSK-3, β-catenin, and Snail signaling." (PMID 37635248, 2023). "Additionally, miR-34a-5p is significantly reduced in CAF-derived exosomes but can be transferred to oral cancer cells, where its overexpression inhibits tumorigenesis by targeting AXL and suppressing proliferation and metastasis via the AKT/GSK-3β/β-catenin pathway." (PMID 39200273, 2024). "The miR-34a-5p/AXL axis could support the progression of OSCC via the AKT/GSK-3/β-catenin signaling pathway, and may promote the EMT to encourage the spread of oral cancer cells." (PMID 37635248, 2023). "Therefore, the miR-34a-5p/AXL axis promotes the proliferation, metastasis, and EMT of oral cancer cells through the AKT/glycogen synthase kinase (GSK)-3β (GSK-3β)/β-catenin/SNAI1 signaling cascade." (PMID 33917482, 2021).